WSB1 (WD repeat and SOCS box containing 1)
Description:
Probable substrate-recognition component of a SCF-like ECS (Elongin-Cullin-SOCS-box protein) E3 ubiquitin ligase complex which mediates the ubiquitination and subsequent proteasomal degradation of target proteins. Recognizes type II iodothyronine deiodinase/DIO2. Confers constitutive instability to HIPK2 through proteasomal degradation.
Synonyms: WSB-1; SWIP1; DKFZp564A122; DKFZp564B0482
Tractability: PROTAC: ubiquitination databases record sites on it.
Gene: Protein-coding gene on chromosome 17 (27,294,067 to 27,315,926, forward strand). Ensembl gene ENSG00000109046.
Subcellular location (Human Protein Atlas): Mitochondria
Pathways (Reactome):
Immune System: Antigen processing: Ubiquitination & Proteasome degradation
Metabolism of proteins: Neddylation
Gene Ontology:
Molecular function: protein binding; ubiquitin protein ligase activity
Biological process: protein polyubiquitination; intracellular signal transduction; protein K27-linked ubiquitination; protein ubiquitination
Cellular component: Lewy body; cytosol; cytoplasm
Genetic constraint (gnomAD): Loss-of-function variants: 22 observed, 48.62 expected, observed/expected ratio (o/e) 0.45, 90% interval 0.32 to 0.65. The upper end of that interval is the gene's LOEUF score, 0.65, which puts it in group 2 of 6, group 1 being the genes least tolerant of losing a copy. Missense variants: 487 observed, 542.32 expected, observed/expected ratio (o/e) 0.9, 90% interval 0.83 to 0.97. Synonymous variants: 179 observed, 179.35 expected, observed/expected ratio (o/e) 1, 90% interval 0.88 to 1.13.
Homologues: Orthologues: chimpanzee WSB1 (99% identical), dog WSB1 (99% identical), pig WSB1 (98% identical), guinea pig WSB1 (96% identical), rabbit WSB1 (94% identical), rat Wsb1 (93% identical), mouse Wsb1 (93% identical), macaque WSB1 (86% identical), tropical clawed frog wsb1 (83% identical), zebrafish wsb1 (75% identical). Paralogues in human: WSB2 (48% identical).
Diseases named in the same sentence as WSB1 in open-access papers:
WSB1 is named in the same sentence as 35 diseases in open-access papers, as found by Europe PMC text mining. Sharing a sentence is not in itself a finding about the gene and the disease. The quoted sentences say what the papers report.
neuroblastoma (6 papers, 2006 to 2025). Neuroblastoma (NB) is the most common solid, extracranial childhood tumor. "The higher expression of WSB1 is significantly associated with a better outcome in neuroblastoma." (PMID 41189817, 2025). "The role of WSB1 in other types of cancer is also controversial; this gene was involved in pancreatic cancer progression and metastatic potential of osteosarcoma, but its high expression was associated with good prognosis and favorable outcome of neuroblastoma." (PMID 32497068, 2020). "In Skov3 ovarian cancer cells, HSYA dose-dependently inhibited proliferation, reduced WD repeat and SOCS box containing 1 (WSB1) gene expression, and enhanced apoptosis, thereby suppressing neuroblastoma and ovarian cancer cell growth." (PMID 40843199, 2025). "WSB1 is overexpressed in stages 1-3 and 4S neuroblastoma tumors compared to stage 4 neuroblastoma tumors." (PMID 41189817, 2025). "WSB1, TRIM4, and RNF144b are associated with multiple cancers including neuroblastoma, chordoma and hepatocellular carcinoma." (PMID 34603387, 2021). "Two groups of investigators, individually studying pancreatic cancer and neuroblastoma, found that the three wsb1 transcripts had antagonistic functions to each other." (PMID 27542736, 2016). "Dysregulation of wsb1 expression has been documented in diverse cancer cell types, including neuroblastoma (NB), hepatocellular carcinoma (HCC), pancreatic, osteosarcoma and breast cancer cells." (PMID 27542736, 2016). "Neuroblastoma cases of stage 4S more frequently showed gains of wsb1 gene copy number than stage 4- cases." (PMID 27542736, 2016). "Copy number changes of wsb1 can be identified in cases of neuroblastoma." (PMID 27542736, 2016). "Increase of wsb1 gene expression correlated with good outcome, suggesting that wsb1 expression may have a role in the biology of good prognosis of certain neuroblastoma." (PMID 27542736, 2016). "For some genes only circumstantial evidence for a role in neuroblastoma is present (WSB1, CDC42, PLAGL1, PRAME and TGFBR3); that we identified these genes in the present study warrants further investigations into their possible role in neuroblastoma development." (PMID 16989664, 2006).
hepatocellular carcinoma (5 papers, 2016 to 2021). A malignant tumor that arises from hepatocytes. "In human hepatocellular carcinoma (HCC) or other cell lines, under hypoxic conditions, WSB1 binds and mediates degradation of HIPK2." (PMID 27542736, 2016).
breast carcinoma (4 papers, 2017 to 2022). "The present study indicates that increased WSB-1 expression is associated with an increased metastatic propensity in ER− and PR− breast cancer patients." (PMID 29540773, 2018). "Downregulation of WSB-1 expression led to decreased angiogenic and invasive potential of HR-negative breast cancer cell lines in vitro and metastatic seeding and growth in vivo." (PMID 29540773, 2018). "The aim of this study was to investigate the role of the E3 ligase WSB-1 in breast cancer biology in the context of the hypoxic tumour microenvironment, particularly regarding metastatic spread." (PMID 29540773, 2018). "In this study, we have shown that high expression of WSB-1 in breast cancer is a marker for increased metastatic disease in HR-negative breast cancer patients." (PMID 29540773, 2018). "High WSB1 expression was associated with decreased DMFS in ER-breast cancer and PR-breast cancer patients." (PMID 29540773, 2018). "Analysis of a larger cohort (TCGA dataset, 1100 patients) also indicated that WSB1 expression is decreased in breast cancer samples." (PMID 29540773, 2018). "This study suggests WSB-1 plays a significant role in breast cancer, particularly in a HR and hypoxic signalling-independent context." (PMID 29540773, 2018). "This study is the first to investigate the role of WSB-1 in breast cancer biology and progression, particularly in HR-independent backgrounds." (PMID 29540773, 2018). "By knocking down the WSB-1 gene in breast cancer cell lines, these investigators found that the downregulation of WSB-1 gene expression levels could significantly decrease the metastatic potential of breast cancer." (PMID 32497068, 2020). "WSB-1 could therefore represent a novel regulator and therapeutic target for secondary breast cancer in these patients." (PMID 29540773, 2018). "So the definite function of WSB1 in breast cancer remains unclear." (PMID 32497068, 2020). "WSB1 was not shown to be consistently up-regulated or down-regulated between normal mammary epithelial cells and breast cancer cells." (PMID 29540773, 2018). "Our study is the first to show that WSB-1 knockdown led to decreased metastatic potential in breast cancer hormone receptor-negative models in vitro and in vivo." (PMID 29540773, 2018). "Taken together, these data indicate that WSB-1 can be induced by HIF1 in hypoxic in breast cancer cell lines, but that this mechanism is unlikely to be the main driver for WSB-1 expression in breast cancers." (PMID 29540773, 2018). "For example, several factors modulate pVHL activity, such as WD repeat and SOCS box-containing protein 1 (WSB1), which was found to promote HIF-1α stabilization and metastases via ubiquitination and degradation of pVHL in renal carcinoma, breast cancer, and melanoma models." (PMID 29230384, 2017). "It is also plausible that WSB-1 could regulate the expression of only a selected number of HIF target genes, rather than all HIF-dependent expression, as it is the case in breast cancer, respectively, for co-factors p300 and DEK for GLUT-1 (SLC2A1) and VEGF (VEGFA) expression." (PMID 29540773, 2018). "Finally, we investigated whether there was any link between the expression of WSB1 and HIF targets SLC2A1, VEGFA, CA9, and HK2 in breast cancer patients." (PMID 29540773, 2018).
melanoma (4 papers, 2017 to 2023). A malignant, usually aggressive tumor composed of atypical, neoplastic melanocytes. "The ubiquitin E3 ligase WD repeat and SOCS box-containing protein 1 (WSB1) was reported to promote melanoma metastasis through targeting pVHL for ubiquitination and degradation." (PMID 36813923, 2023).
Parkinson disease (3 papers, 2016 to 2024). A progressive degenerative disorder of the central nervous system characterized by loss of dopamine producing neurons in the substantia nigra and the presence of Lewy bodies in the substantia nigra and locus coeruleus. "Recent data suggests a new role for WSB1 as a component of a neuroprotective pathway which results in modification and aggregation of neurotoxic proteins such as LRRK2 in Parkinson’s Disease, via an unusual mode of protein ubiquitinylation." (PMID 27542736, 2016).
bladder cancer (2 papers, 2017 to 2022). "In conclusion, we demonstrated that AE-AS exhibits a potent antiangiogenic activity in bladder cancer through suppressing WSB-1-induced pVHL degradation, HIF-1α induction/activity, and angiogenesis-related signaling pathways." (PMID 28710377, 2017). "Our data showed that knocking down WSB-1 with si-WSB-1 markedly reversed the elevation of nuclear HIF-1α level and VEGF synthesis in hypoxic T24 cells, indicating that WSB-1 plays a crucial role in the activation of HIF-1α/VEGF cascade in bladder cancer." (PMID 28710377, 2017). "Consistently, hypoxia-induced nuclear HIF-1α level and VEGF synthesis in T24 cells was greatly reduced by si-WSB-1, indicating that WSB-1 also stimulates the HIF-1α/VEGF cascade in bladder cancer." (PMID 28710377, 2017).
pancreatic cancer (2 papers, 2008 to 2020). "In this paper we describe a panel of potential pancreatic cancer genes selected using a xenograft strategy and analyze the structure and function of one of them, the WSB1 gene, in relation to pancreatic tumor progression." (PMID 18575577, 2008). "In conclusion, we report that the shift in WSB1 isoform expression observed in human pancreatic cancer cells submitted to a stress is similar to the shift observed when these cells are xenografted in nude mice or in human pancreatic tumors." (PMID 18575577, 2008). "The physiological consequences for pancreatic cancer cells of stress-induced changes in the proportions of WSB1 isoforms, in terms of growth rate and resistance to apoptosis, are important." (PMID 18575577, 2008). "This suggests that the expression profile of WSB1 observed in mice xenografts is representative of what happens in human pancreatic cancer." (PMID 18575577, 2008). "In xenografts and in human pancreatic tumors, global expression of WSB1 mRNA is modestly increased whereas isoform 3 is strongly overexpressed and isoforms 1 and 2 are down-regulated." (PMID 18575577, 2008).
acute pancreatitis (1 paper, 2024). An acute inflammatory process that leads to necrosis of the pancreatic parenchyma. "Further screening identified four genes (ACSL4, GALNT3, WSB1, and IL1R1) that were significantly upregulated in severe acute pancreatitis (SAP) in both human and mouse samples." (PMID 38862656, 2024).
angiosarcoma (1 paper, 2024). A malignant tumor arising from the endothelial cells of the blood vessels. "• In rat and human angiosarcoma, miR-23 target genes (Ccnd1, Adam19, Plau, and Wsb1) that increase invasiveness and metastasis were enriched." (PMID 38826780, 2024).
COVID-19 (1 paper, 2021). A disease caused by infection with severe acute respiratory syndrome coronavirus 2. "Another preprint leading with supervariants involved in COVID-19 mortality focuses on the possible role of rs60811869, an eQTL of gene of the E3 ubiquitin ligase WD Repeat And SOCS Box Containing 1 (WSB1), in determining death rates among COVID-19 patients." (PMID 33807915, 2021).
Fanconi anemia (1 paper, 2025). Fanconi anemia (FA) is a hereditary DNA repair disorder characterized by progressive pancytopenia with bone marrow failure, variable congenital malformations and predisposition to develop hematological or solid tumors. "Six hub genes (FANCI, KAT2A, TACC3, TPX2, VHL, WSB1) were enriched in Fanconi anemia and HIF-1 pathways, affecting microtubules, spindle formation, and cytoskeleton dynamics during mitosis." (PMID 40832468, 2025).
helminth infections (1 paper, 2021). "There is no previous study describing the role of WSB1 in helminth infections or any other Th2-driven condition." (PMID 33692795, 2021).
metastatic disease (1 paper, 2018). "Our data suggests that WSB-1 may be an important regulator of aggressive metastatic disease in hormone receptor-negative breast cancer." (PMID 29540773, 2018).
myocardial infarction (1 paper, 2024). Gross necrosis of the myocardium, as a result of interruption of the blood supply to the area, as in coronary thrombosis. "WSB1 was found highly expressed in penumbra of myocardial IR rats, and the WSB1 overexpression relieved IR-induced cardio dysfunction, myocardial infarct and pathological damage, and cardiomyocyte death in penumbra." (PMID 38395742, 2024). "The TTC staining of pale region notarized that IR-induced myocardial infarction was mitigated by WSB1 overexpression." (PMID 38395742, 2024).
myocardial ischemia (1 paper, 2024). A disorder of cardiac function caused by insufficient blood flow to the muscle tissue of the heart. "Here, we speculated that WSB1 may play a protective role in myocardial ischemia and regulate β-catenin signaling by mediating GSK3β degradation." (PMID 38395742, 2024).
Obesity (1 paper, 2020). Accumulation of substantial excess body fat. "Some of these SNP loci were linked to genes, such as Wsb1, Snap29 and Aplp2, suggesting that they play a role in obesity development." (PMID 32273571, 2020).
osteoarthritis (1 paper, 2023). A noninflammatory degenerative joint disease occurring chiefly in older persons, characterized by degeneration of the articular cartilage, hypertrophy of bone at the margins and changes in the synovial membrane. "We therefore consider these approaches, including the study of osteoarthritis development in surgical and aging models, as the next steps in our quest to understand the role of NDRG2, WSB1, JMJD6, TSPYL2, HMGB2 and PPP1R15A in osteoarthritis and their inner mechanistic links." (PMID 37033917, 2023).
pancreatic adenocarcinoma (1 paper, 2008). "To check the clinical relevance of these findings, we measured the expression of the WSB1 isoforms by quantitative RT-PCR in 8 human pancreatic adenocarcinoma samples." (PMID 18575577, 2008).
prostate carcinoma (1 paper, 2023). A carcinoma that arises from epithelial cells of the prostate gland. "Taken together with the previously reported association between elevated WSB1 expression and high tumor grade, these survival data demonstrated that WSB1 overexpression was correlated with unfavorable prognosis, suggesting WSB1 as a clinical biomarker for prostate cancer." (PMID 37628609, 2023).
cancer (21 papers, 2008 to 2025). A tumor composed of atypical neoplastic, often pleomorphic cells that invade other tissues. "Furthermore, studies of cancer specimens have identified dysregulation of wsb1 associated with several types of cancer, suggesting a biologically relevant role in cancer development and/or progression." (PMID 27542736, 2016). "The results unveil a novel PRDX5/GPX4/SIAH2/WSB1 signaling axis as a promising therapeutic vulnerability for cancer." (PMID 40831323, 2025). "Specifically, in these studies, authors have shown that WD repeat and SOCS box-containing protein 1 (WSB1) can stabilize HIF-1α by ubiquitinating VHL in cancer cells." (PMID 39119289, 2024). "In fact, regulation of cellular response to hypoxia has been shown as only one of the key regulator functions of WSB1 and other protein targets of WSB1 are also involved in other cancer pathways." (PMID 37628609, 2023). "Using data from the Cancer Genome Atlas, we tested the possible involvement of WSB1 in PC progression." (PMID 37628609, 2023). "WSB1 (hypoxia-driven-WD repeat and SOCS box containing 1) is upregulated in many human cancers and acts as a suppressor of cytokine signaling." (PMID 36835422, 2023). "C-myc is demonstrated to be involved not only in tumor initiation, but also in cancer progression, an important point to keep in mind considering that WSB1 was also reported as a direct target gene of c-myc." (PMID 37628609, 2023). "Based on the results in literature regarding other cancer types, we tested the possible involvement of WSB1 in PC progression." (PMID 37628609, 2023). "WSB1 promotes cancer progression by affecting the Von Hippel–Lindau tumor suppressor protein (pVHL) and upregulating hypoxia inducible factor-1α (HIF-1α) target gene expression." (PMID 35600960, 2022). "Previous studies have analyzed levels of WSB1 expression in the brain, spleen, kidney and placenta, primarily with research focusing on cancer development." (PMID 33692795, 2021). "Specimens of HCC from cancer patients showed a general inverse correlation between miR-592 levels and the levels of WSB1 and HIF1α." (PMID 27542736, 2016). "Likely through its latter effects, WSB1 has been shown to be a likely regulator of abnormal proliferation and metastasis in cancer." (PMID 27542736, 2016). "RNAi silencing of wsb1 in cancer cells under normoxia and hypoxia treatment stabilizes VHL, while inhibition of the WSB1 effect with MG132, a proteasome inhibitor, led to VHL survival." (PMID 27542736, 2016). "This was identified through the xenotransplantation of respective cancer cells in mouse, and quantifying the wsb1 mRNA in the extract by real-time PCR (qPCR)." (PMID 27542736, 2016). "As well, recent work has identified a role for WSB1 in glucose metabolism, and perhaps in mediating the Warburg effect in cancer cells by maintaining the function of HIF1." (PMID 27542736, 2016). "A class of target genes with the potential to increase the early cancer identification and tumor development is constituted by those involved in DNA damage response by targeting homeodomain-interacting protein kinase 2, such as WSB1." (PMID 37628609, 2023). "Besides transcriptional regulation by oncogenic transcription factors, such as c-Myc, HIF-1, and CREB-ATF36,37, our study provides another mechanism of WSB1 expression regulation in cancer cells, which is via DAP3-modulated alternative splicing." (PMID 35379802, 2022). "Collectively, AE-AS may be a potential anticancer agent by attenuating cancer angiogenesis via suppression of WSB-1/pVHL/HIF-1α/VEGF/VEGFR2 cascade." (PMID 28710377, 2017). "The wsb1 gene has been identified to be important in developmental biology and cancer." (PMID 27542736, 2016). "Regulation of multiple, important regulatory proteins by WSB1 in the cellular response to hypoxia, may also facilitate cancer phenotypes." (PMID 27542736, 2016).